IL27RA (interleukin 27 receptor subunit alpha)
Description:
Signal-transducing subunit for an heterodimeric cytokine composed of IL27/p28 and a soluble receptor EBI3. Heterodimerizes with IL6ST/GP130 to mediate signal transduction in response to the heterodimeric cytokine IL27/p28-EBI3. This signaling system acts through STAT3 and STAT1. Also acts as a signaling receptor as part of the humanin receptor complex; binding of MT-RNR2/humanin (HN) activates the intracellular JAK-STAT3 signaling pathway leading to neuroprotection. Involved in the regulation of Th1-type immune responses (By similarity). Also appears to be involved in innate defense mechanisms.
Synonyms: IL-27RA; TCCR; CRL1; WSX1; WSX-1; zcytor1; IL-27R; IL27R
Tractability: Antibody: its Gene Ontology location is reachable by antibodies, with high confidence; UniProt predicts a signal peptide or a membrane-spanning region. PROTAC: ubiquitination databases record sites on it.
Gene: Protein-coding gene on chromosome 19 (14,031,644 to 14,053,223, forward strand). Ensembl gene ENSG00000104998.
Subcellular location: Membrane
Subcellular location (Human Protein Atlas): Vesicles
Pathways (Reactome):
Immune System: Interleukin-27 signaling; Interleukin-35 Signalling
Gene Ontology:
Molecular function: protein binding; interleukin-27 receptor activity; signaling receptor activity; transmembrane signaling receptor activity
Biological process: negative regulation of neuron apoptotic process; cell surface receptor signaling pathway; cell surface receptor signaling pathway via JAK-STAT; immune response; interleukin-27-mediated signaling pathway; negative regulation of apoptotic process; negative regulation of T-helper 1 type immune response; negative regulation of type 2 immune response; positive regulation of interleukin-10 production; positive regulation of MAPK cascade; regulation of B cell proliferation; negative regulation of cellular extravasation; negative regulation of interleukin-17 production; negative regulation of interleukin-6 production; negative regulation of T cell extravasation; negative regulation of T-helper 17 type immune response; negative regulation of tumor necrosis factor production
Cellular component: humanin receptor complex; plasma membrane; receptor complex; membrane
Genetic constraint (gnomAD): Loss-of-function variants: 61 observed, 80.66 expected, observed/expected ratio (o/e) 0.76, 90% interval 0.61 to 0.94. The upper end of that interval is the gene's LOEUF score, 0.94, which puts it in group 3 of 6, group 1 being the genes least tolerant of losing a copy. Missense variants: 721 observed, 807.45 expected, observed/expected ratio (o/e) 0.89, 90% interval 0.84 to 0.95. Synonymous variants: 314 observed, 332.99 expected, observed/expected ratio (o/e) 0.94, 90% interval 0.86 to 1.03.
Homologues: Orthologues: macaque IL27RA (94% identical), dog IL27RA (77% identical), pig IL27RA (75% identical), chimpanzee IL27RA (75% identical), rabbit IL27RA (66% identical), mouse Il27ra (62% identical), rat Il27ra (62% identical), guinea pig IL27RA (61% identical), zebrafish lifrb (15% identical), zebrafish lifra (15% identical), zebrafish ghra (10% identical), zebrafish il2rga (8% identical), and 6 more. Paralogues in human: IL12RB2 (23% identical), CSF3R (22% identical), IL6ST (16% identical), LIFR (16% identical), OSMR (15% identical), IL31RA (14% identical), IL12RB1 (12% identical), IL23R (12% identical), LEPR (11% identical), PRLR (11% identical), CRLF1 (9% identical), GHR (9% identical), and 11 more.
Diseases named in the same sentence as IL27RA in open-access papers:
IL27RA is named in the same sentence as 115 diseases in open-access papers, as found by Europe PMC text mining. Sharing a sentence is not in itself a finding about the gene and the disease. The quoted sentences say what the papers report.
melanoma (9 papers, 2011 to 2024). A malignant, usually aggressive tumor composed of atypical, neoplastic melanocytes. "For the melanoma cell line, A375, IL-27Rα was minimally detected, while gp130 was abundantly present at the surface level." (PMID 27119567, 2016). "The murine B16F10 melanoma cell line used in mouse models does not express the IL-27Rα chain and does not respond to IL-27." (PMID 24130734, 2013).
breast carcinoma (8 papers, 2013 to 2026). "To explore IL-27 signaling in the tumor stroma, we used a mammary carcinoma syngraft approach in IL27Rα-deficient mice." (PMID 31637217, 2019). "To further explore the role of IL-27 in tumor stromal cells, we used a mammary carcinoma cell syngraft approach in IL27Rα-deficient mice." (PMID 31637217, 2019). "Here, we test the initiation and growth of carcinogen-induced fibrosarcomas and oncogene-driven mammary carcinomas in Il27ra deficient mice." (PMID 23554861, 2013). "We utilized MDA-MB231 as a positive control since it is a breast-cancer cell line that is reported to overexpress IL-27Rα on the cell surface." (PMID 35200430, 2022). "IFN-γ production was found to be significantly reduced in the CD4+CD44+ T cell compartment in Il27ra−/− compared to Il27ra+/+ mice in both the fibrosarcoma and mammary carcinoma models." (PMID 23554861, 2013). "We therefore tested the growth of established primary mammary carcinomas upon direct transfer to naive Il27ra+/+ and Il27ra−/− hosts." (PMID 23554861, 2013). "Research on IL27RA in breast cancer highlights the role of immune checkpoint signaling in tumor progression, suggesting that ligand-engineered RNVs could concurrently deliver therapeutic agents and modulate inhibitory pathways." (PMID 41216197, 2025). "In parallel, emerging immune-metabolic regulators such as IL27RA and TMEM71 have been identified through single-cell and integrative transcriptomic analyses as potential prognostic and therapeutic indicators in breast cancer." (PMID 41398603, 2025).
Sepsis (8 papers, 2018 to 2025). Sepsis is defined as life-threatening organ dysfunction caused by a dysregulated host response to infection. "Our laboratory studied the transcriptome of the neonatal spleen during Escherichia coli-induced sepsis in wild-type (WT) and IL-27Rα-deficient (KO) mice." (PMID 40977737, 2025). "To explore a reprogramming of the host response in the absence of IL-27 signaling, we profiled the transcriptome of the neonatal spleen during Escherichia coli-induced sepsis in wild-type (WT) and IL-27Rα-deficient (KO) mice." (PMID 36891292, 2023). "Analysis of the transcriptome of the neonatal spleen during Escherichia coli-induced sepsis in IL-27Rα KO mice identified elevated expression of the chemokine receptor gene CXCR2." (PMID 40977737, 2025). "Here, we explored the mechanism by which elevated levels of CXCR2 aid in combating sepsis in IL-27Rα KO neonatal mice." (PMID 40977737, 2025). "In a neonatal murine E. coli sepsis model, IL-27Rα-/- mice showed lower levels of TNF-α, IL-1β and IL-6, and improved survival rates." (PMID 34079555, 2021).
colitis (7 papers, 2013 to 2024). Inflammation of the colon. "This conclusion is made based on the T-cell-induced colitis model using lymphopenic mice deficient in IL-27Rα." (PMID 25126585, 2014). "Additionally, in another model of T-cell-mediated colitis, transfer of IL-27Rα−/− T-cells resulted in diminished weight loss and reduced intestinal inflammation when compared to transferring wild-type T-cells." (PMID 33435303, 2021). "Moreover, in a model of helminth-induced inflammatory bowel disease (IBD), Il27ra deficiency impaired Th1 responses in the intestine resulting in inefficient worm expulsion and delayed onset of colitis." (PMID 31379810, 2019). "On the other hand, IL-27Rα−/− mice developed less severe colitis after DSS treatment when compared to their wild-type controls, characterized by reduction in inflammatory cytokines (IL-6, TNF, and IFN-γ)." (PMID 33435303, 2021). "The study that transferred IL-27rα−/−CD45Rbhi T cells into CB17-SCID mice found inhibited colitis." (PMID 38566992, 2024). "While IL-27Rα+ lymphopenic mice that receive naïve CD4 T cells develop chronic colitis associated with colitogenic Th1 and Th17 type effector cell generation, lymphopenic mice deficient in IL-27Rα are completely protected from the colitis after the T cell transfer." (PMID 25126585, 2014). "When cotransferring naive T cells from IL-27rα−/− mice with B cells from WT mice into B6 DKO mice, there was severe colitis, and IFNγ and IL-17A expression in colonic tissue explants was increased and IL-10 expression was reduced." (PMID 38566992, 2024). "However, transferring IL-27rα−/− Treg cells into colitis mouse models did not inhibit inflammatory T-cell responses." (PMID 38566992, 2024).
parasitemia (7 papers, 2014 to 2021). "The absence of Ebi3 or IL-27Rα was also associated with a higher parasitemia after the experimental infection with 500 forms of the Tulahuen strain of T. cruzi." (PMID 29033934, 2017). "In addition, neutralization of IL-4 in IL-27Rα-deficient mice or inhibition of Arginase-1 in Ebi3-deficient mice was essential to control the parasitemia, but did not alter the host survival." (PMID 29033934, 2017).
influenza infection (5 papers, 2014 to 2024). "Transferring splenocytes from IL-27rα−/− mice into lymphocyte-deficient Rag2−/−γc−/− mice followed by influenza infection showed lower expression of IFNγ." (PMID 38566992, 2024). "al, which demonstrated accelerated weight loss in IL-27Rα−/− mice during influenza infection." (PMID 25651926, 2015). "In our current study, preceding influenza enhanced susceptibility to secondary S. aureus pneumonia in both WT and IL-27Rα−/− mice, although the bacterial burden was significantly reduced in the co-infected IL-27Rα−/− mice compared to co-infected WT mice." (PMID 25651926, 2015). "IL-27rα−/− mice infected with influenza showed a reduction in the percentage of CD27+CD11b+ NK cells in the alveolar space and in the bone marrow and less NK T cells were recruited to the bronchoalveolar space." (PMID 38566992, 2024). "In our current study, we observed increased IFNγ protein levels in the influenza-infected IL-27Rα−/− mice compared to WT, confirming that IL-27 signaling attenuates IFNγ production during influenza infection." (PMID 25651926, 2015). "We examined levels of IL-10 production in both WT and IL-27Rα−/− mice co-infected with influenza, S. aureus." (PMID 25651926, 2015). "In the IL-27Rα−/− mice, there was also significantly decreased clearance of S. aureus in the mice that received preceding influenza compared to the mice that received S. aureus alone." (PMID 25651926, 2015). "Because IL-10 production was severely decreased in influenza infected IL-27Rα−/− mice compared to controls, we proposed that IL-27 induction of IL-10 might play a role in the development of secondary S. aureus pneumonia." (PMID 25651926, 2015). "However, both WT and IL-27Rα−/− co-infected mice had significantly increased airway inflammation compared to mice singularly infected with S. aureus or influenza." (PMID 25651926, 2015). "Finally, we investigated influenza, S. aureus co-infection and IL-27Rα−/− mice exhibited increased bacterial clearance compared to controls." (PMID 25651926, 2015). "Importantly, co-infected IL-27Rα−/− mice have increased production of IL-17 F and IL-22 compared to co-infected WT mice, suggesting that IL-27 signaling significantly impacts Type 17 immunity during influenza, S. aureus co-infection." (PMID 25651926, 2015). "We therefore investigated the impact of IL-27 and its receptor IL-27Rα on immunopathology using the highly mouse pathogenic strain A/PR/8 (H1N1) and subsequently explored the therapeutic potential of recombinant IL-27 (rIL-27) to treat inflammatory lung disease in influenza." (PMID 24809349, 2014). "Ebi3−/− and Il27ra−/− mice exhibited significantly reduced NK cell effector functions (IFN-γ and cytotoxicity) during influenza infection." (PMID 30899058, 2019). "We found a significant reduction in the percentages of CD27+CD11b+ NK cell effector population in the alveolar space of Il27ra−/− but not WT in influenza-infected mice." (PMID 30899058, 2019). "Lack of IL-27Rα (Wsx1) or IL-27 subunit EBI3 resulted in impaired NK cell-mediated effector functions and ineffective clearance of influenza infection." (PMID 30899058, 2019).
atherosclerosis (4 papers, 2017 to 2020). A disease characterized by the build-up of fatty material and calcium deposition in the arterial wall resulting in partial or complete occlusion of the arterial lumen. "Hematopoietic ablation of Il27ra accelerated atherosclerosis due to enhanced activation of CD4+ T cells, in particular, Th17 cells, accompanied by increased IL-17A, TNF-α and IL-6 production, CCL2 chemokine expression and accumulation of myeloid cells." (PMID 28536468, 2017). "Our data in Apoe−/− model of atherosclerosis argues for an important anti-inflammatory role of IL-27R signaling in myeloid cell compartment as demonstrated by the analysis of myeloid subsets composition and activation status in atherosclerotic Apoe−/−Il27ra−/− mice." (PMID 28536468, 2017).
Autoimmunity (4 papers, 2011 to 2025). The occurrence of an immune reaction against the organism's own cells or tissues. "Importantly, IL-27 receptor-deficient (IL27RA–/–) mice have been shown to develop exaggerated pro-inflammatory T-cell responses and autoimmunity, suggesting that IL-27 to also inhibits tissue inflammation, possibly via induction of type 1 regulatory cells (Tr1) cells." (PMID 33717163, 2021).
lupus (4 papers, 2011 to 2025). "In lupus-prone MRL/lpr mice, Th1:Th2 balance shifts to Th2-immunity by IL-27Rα deficiency, resulting in a Th2-mediated immunopathology similar to human membranous glomerulonephritis." (PMID 25633106, 2015). "IL-27Rα overexpression is reported to suppress antibody production in lupus-prone MRL-Faslpr/lpr (MRL/lpr) mice." (PMID 25633106, 2015). "Considering the differences between IL-27rα−/−Roquinsan/san mice, pristane-treated IL-27rα−/− mice, and IL-27rα−/− MRL/lpr mice, several aspects may correlate with different results of lupus development, such as different mouse models and differences in the experimental setup." (PMID 38566992, 2024).
malaria (4 papers, 2013 to 2025). Malaria is a serious and sometimes fatal disease caused by a parasite that commonly infects a certain type of mosquito which feeds on humans. "The malaria-responsive expression of Il27ra was initially decreased on day 1 p.i., then increased on day 4 p.i., and this expression level was maintained until day 11 p.i. in vaccination-protected mice compared to unvaccinated mice." (PMID 40243929, 2025). "The genes Il27 and Il27ra were constitutively expressed in the liver, and their expressions were malaria-responsive, but only Il27ra was also significantly responsive to vaccination." (PMID 40243929, 2025).
Obesity (4 papers, 2020 to 2024). Accumulation of substantial excess body fat. "After further analyses of these shared gene-sets, overexpressed pro-inflammatory cytokines and cytokine receptors (e.g., IL11, IL20RA, IL27RA) could be linked to less thermogenic DN adipocytes, and thereby, to obesity and inflammation." (PMID 32316277, 2020).
Arthritis (3 papers, 2011 to 2024). Inflammation of a joint. "IL-27rα+/+ mice immunized with proteoglycan (PG) had characteristics of arthritis, and development of arthritis was suppressed in IL-27rα−/− mice." (PMID 38566992, 2024). "For example, IL-27rα−/− mice were protected against arthritis, whereas the addition of IL-27 to collagen- and osteocollagenesis-induced arthritis may inhibit arthritis development." (PMID 38566992, 2024).
asthma (3 papers, 2017 to 2024). "In a murine asthma model, WSX-1 deficient mice (also known as IL-27Rα−/− mice) exhibited enhanced lung pathology, characterized by goblet cell hyperplasia, infiltration of eosinophils, elevated serum IgE, and airway hyperresponsiveness." (PMID 29118754, 2017).
viral infection (3 papers, 2014 to 2022). "Additionally, NK cell production of granzyme B, a protease that kills virus-infected cells, was diminished in il27rα-/- mice and associated with reduced viral clearance, suggesting a role of IL-27 in mediating NK cell effector functions during virus infection." (PMID 35634328, 2022). "Significant reductions in IL-10-producing CD4+ and CD8+ T cells are observed during viral infection in il27ra-/- and ebi3-/- mice compared to their WT counterparts." (PMID 35634328, 2022). "The absence of IL-27Rα signaling during acute virus infection worsened immunopathology and disease course; this ultimately resulted in increased mortality, despite controlled viral loads." (PMID 24809349, 2014).
acute myeloid leukemia (2 papers, 2013 to 2016). Acute myeloid leukemia (AML) is a group of neoplasms arising from precursor cells committed to the myeloid cell-line differentiation. "In patients with acute myeloid leukemia, IL-27Rα has been linked to transformation through its ability to dimerize and to constitutively activate a mutant form of Jak2." (PMID 24130734, 2013).
airway hyperresponsiveness (2 papers, 2017 to 2024). "IL-27Rα gene knockout leads to increased airway hyperresponsiveness and airway inflammation in asthmatic mice." (PMID 38117410, 2024).
Alzheimer disease (2 papers, 2018 to 2023). A progressive, neurodegenerative disease characterized by loss of function and death of nerve cells in several areas of the brain leading to loss of cognitive function such as memory and language. "This truncated IL-27Rα isoform acted as a functional subunit of a receptor for an anti-Alzheimer’s disease rescue factor Humanin31." (PMID 29985424, 2018).
colorectal cancer (2 papers, 2022 to 2023). A primary or metastatic malignant neoplasm that affects the colon or rectum. "It is not known if IL-27 or its specific receptor IL-27Rα is increased in human colorectal cancer, nor the biological consequence of this." (PMID 35336801, 2022).
diabetes (2 papers, 2024 to 2025). "On the other hand, NOD mice lacking IL-27 or IL-27Rα completely resist diabetes development." (PMID 41027725, 2025). "Co-transfer of CD4+ and CD8+ T cells from NOD mice into Rag1−/− NOD mice upregulated the incidence of diabetes, whereas co-transfer of CD4+ and CD8+ T cells from IL-27rα−/− NOD mice into Rag1−/− NOD mice did not induce diabetes, demonstrating that IL-27 signaling is essential for T1D development." (PMID 38566992, 2024).
Granuloma (2 papers, 2014 to 2021). A compact, organized collection of mature mononuclear phagocytes, which may be but is not necessarily accompanied by accessory features such as necrosis. "In contrast to C57BL/6 mice, which show rather unstructured granulomatous lesions upon Mtb infection, granulomas in IL-27Rα-/- mice are highly stratified containing a centre of infected MΦ surrounded by a pronounced rim of B and T lymphocytes." (PMID 35116036, 2021). "Accordingly, in Mtb-infected IL-27Rα-/- mice, IL-17A mediates the early accumulation of neutrophils in the centres of organized granulomas." (PMID 35116036, 2021). "In the absence of IL-27Rα, Mtb-infected lungs exhibit highly structured granulomas surrounded by a lymphocyte rim which predominantly contains clusters of B cells - an effect that is strikingly dependent on the expression of IL-17A." (PMID 35116036, 2021). "Moreover, the generation of highly stratified granulomas in the Mtb-infected IL-27Rα-/- mice is strikingly dependent on IL-17A, which is not surprising given that the impact of IL-17A on TB granuloma formation has been described before." (PMID 35116036, 2021).